PCBP2 (poly(rC) binding protein 2)
Diseases named in the same sentence as PCBP2 in open-access papers (continued):
Sharing a sentence is not in itself a finding about the gene and the disease.
ovarian carcinoma (1 paper, 2023). A malignant neoplasm originating from the surface ovarian epithelium. "The expression of CYBRD1, LRP2, TFRC, SLC22A17, HEPH, SLC39A14, and PCBP2 involved in iron import was associated with poor OS of ovarian cancer, whereas the expression of LCN2, CP, SLC46A1, STEAP3, and LTF in this process was associated with improved OS in ovarian cancer." (PMID 38186569, 2023).
pulmonary sarcoidosis (1 paper, 2016). Sarcoidosis affecting the lung parenchyma. "In line with this hypothesis, we observed the correlation between PCBP2 mRNA and BA lymphocyte sub-population in our patients with pulmonary sarcoidosis." (PMID 27575817, 2016). "Regarding cellular profile of BAL (bronchoalveolar lavage), the BA relative expression of PCBP2 mRNA showed negative correlations with absolute and relative numbers of lymphocytes (p = 0.003 and p = 0.003) in the patient group of pulmonary sarcoidosis." (PMID 27575817, 2016).
sarcoidosis (1 paper, 2016). Sarcoidosis is a multisystemic disorder of unknown cause characterized by the formation of immune granulomas in involved organs. "In contrast to PCBP2, the mRNA expression of other RBPs and two inhibitors of MMP-9 (RECK and PTEN) did not correlate with any BA sub-population in our patients with sarcoidosis." (PMID 27575817, 2016).
urogenital cancers (1 paper, 2023). "Furthermore, we identified alternative splicing of GIT2 and TUBB3 and RNA binding proteins such as PCBP2 as critical regulators in the progression of urogenital cancers." (PMID 37810965, 2023). "Furthermore, we identified and validated alternative splicing of TUBB3 and RNA binding proteins such as PCBP2 as critical regulators in the progression of urogenital cancers." (PMID 37810965, 2023).
tumor (31 papers, 2015 to 2025). "Our study demonstrated that disrupting angiogenesis-associated miRNA sorting through PCBP2 depletion notably reduced the microvessel density in murine tumor tissues." (PMID 39816681, 2025). "In summary, we have unveiled the pivotal role and underlying mechanism of EGFR in promoting tumor angiogenesis by controlling the PCBP2-dependent miRNA sorting into sEVs." (PMID 39816681, 2025). "MiR-214 regulates tumor progression by targeting mRNAs encoding proteins such as poly(rC) binding protein-2 (PCBP2), E2F transcription factor 2 (E2F2), and the SUMO-conjugating enzyme UBC9." (PMID 29862267, 2018). "In addition, overexpression of PCBP2 reversed the tumor-suppressing function caused by sh-KCNQ1OT in BC." (PMID 31827399, 2019). "We confirmed that PCBP2 plays a crucial role in promoting EGFR-driven tumor angiogenesis both in vivo and in vitro, by controlling the secretion of these EVmotif-containing miRNAs." (PMID 39816681, 2025). "Analysis of Ti-sEVs obtained from OSCC patients further validated that PCBP2 was more abundant in tumor Ti-sEVs compared to paired normal mucosa Ti-sEVs." (PMID 39816681, 2025). "In the end, we verified the significance of PCBP2-driven miRNA secretion via sEVs in promoting tumor angiogenesis in vivo." (PMID 39816681, 2025). "The miR‐5195‐3p overexpression suppressed tumor cell behaviors, effects that were partially reversed by PCBP2 reintroduction." (PMID 40740483, 2025). "PCBP2 was chosen for additional analysis among these genes due to its significantly higher expression in tumor tissues than in normal tissues." (PMID 40051782, 2025). "Deletion of PCBP2 markedly decreased intra-tumoral microvessel density, resulting in more focal necrosis within the tumor tissues." (PMID 39816681, 2025). "GPX4, PCBP1, and PCBP2 protein levels were reduced in tumor tissues in a dose-dependent manner, which was consistent with the results of the in vitro experiments." (PMID 40619432, 2025). "Our study broadens the understanding of PCBP2's RNA regulatory functions by exploring its role in miRNA secretion, offering new insights into its involvement in tumor progression." (PMID 39816681, 2025). "PCBP2 has been identified as a key regulator of tumor progression through its modulation by ubiquitination." (PMID 39430249, 2024). "PCBP2 depletion decreases GC cell viability and proliferation and inhibits cell proliferation, colony formation, migration, invasion, in vivo tumor growth, and metastasis in BC." (PMID 37834160, 2023). "Immunofluorescence of mouse subcutaneous tumor tissue also confirmed the down-regulation of PCBP2 protein expression after the knock-down of PHGDH." (PMID 36147463, 2022). "It has been reported that the combination of gemcitabine with the silencing of PCBP2 can markedly suppress tumor progression in a desmoplastic PDAC orthotopic mouse model." (PMID 36038612, 2022). "The weights of harvested tumors were consistent with the bioluminescence results, showing that combination of the CCP/PCBP2 siRNA nanocomplex and gemcitabine chemotherapy resulted in a 72.3% reduction in tumor weights." (PMID 33500719, 2021). "The tumor spheroids treated with the CCP/PCBP2 siRNA nanocomplex exhibited a higher fluorescence intensity and deeper penetration of Hoechst 33258 at 2 h and 4 h of incubation than cells treated with the CCP/scrambled siRNA nanocomplex." (PMID 33500719, 2021). "Various in vitro studies were performed to evaluate the silencing activity, cellular uptake, serum stability, and tumor penetration of the PCBP2 siRNA nanocomplex." (PMID 33500719, 2021). "In contrast, treatment with the CCP/PCBP2 siRNA nanocomplex plus gemcitabine significantly inhibited tumor progression compared to the other treatments." (PMID 33500719, 2021).
tumor (continued). "In contrast, the combination of gemcitabine and the CCP/PCBP2 siRNA nanocomplex resulted in the greatest inhibition of collagen expression in the tumor, as it reduced collagen expression by 46.8%." (PMID 33500719, 2021). "The combination of gemcitabine with the PCBP2 siRNA nanocomplex markedly suppresses the tumor progression in a desmoplastic PDAC orthotopic mouse model." (PMID 33500719, 2021). "In the present study, treatment with the CCP/PCBP2 siRNA nanocomplex improved the penetration of small molecules into the stroma-rich tumor spheroids." (PMID 33500719, 2021). "PCBP2 is a member of the PCBP family that regulates tumor development and is actively involved in posttranscriptional and translational regulation by interacting with single-stranded poly(C) motifs in target mRNAs." (PMID 31591350, 2019). "In line with this hypothesis, the depletion of PCBP2 notably abolished the EGFR-driven tumor angiogenesis in vivo." (PMID 39816681, 2025). "Additionally, depletion of PCBP2 impaired the EGFR-driven tumor angiogenesis by inhibiting the secretion of pro-angiogenic miRNAs through sEVs." (PMID 39816681, 2025). "Given the significance of the cGAS-STING pathway in tumor immune evasion, we are determined to investigate whether PCBP2 influences Pca growth through this pathway." (PMID 40051782, 2025). "Interestingly, PCBP2 was an RNA-binding protein that was involved in regulating and stabilizing the mRNA translation of cancer-related protein in tumor cells, and further regulating the development of cancer." (PMID 37814239, 2023). "PCBP2 is considered to be a promoter of tumor proliferation and progression." (PMID 36147463, 2022). "We describe a nano-engineering approach to deliver the PCBP2 siRNA for the homoeostatic restoration of the fibrotic tumor stroma in combination with chemotherapy, leading to increased drug delivery into the tumor microenvironment and killing tumor cells at “home”." (PMID 33500719, 2021). "Therefore, the beneficial modulation induced by the PCBP2 siRNA nanocomplex improved drug penetration into the tumor microenvironment, thus increasing the chemotherapeutic efficacy of gemcitabine in vivo." (PMID 33500719, 2021). "Here, we evaluated whether the CCP/PCBP2 siRNA nanocomplex downregulates stroma and subsequently improves the penetration of small molecule chemotherapy drug in stroma-rich 3D tumor spheroids." (PMID 33500719, 2021). "MiR-145-5p inhibition and PCBP2 up-regulation could countervail the tumor-inhibitor role of KCNQ1OT1 knockdown in BC." (PMID 31827399, 2019). "In general, PCBP2 upregulation can rescue tumor-inhibitor role of KCNQ1OT1 depletion in BC." (PMID 31827399, 2019). "PCBP2 was reported to play a tumor facilitator role in several cancers." (PMID 31827399, 2019). "Several studies have shown that PCBP2 may promote tumor growth." (PMID 34868263, 2021). "EGFR overexpression also strengthened the binding of PCBP2 with miRNAs containing this “GGGU” motif, thereby promoting their secretion through sEVs to support tumor angiogenesis." (PMID 39816681, 2025). "Meanwhile, subcutaneous tumor model and lung metastasis model were used to validate the functional role of the HNF4A-AS1/PCBP2/AGR2 axis in vivo." (PMID 39430249, 2024). "Our results identified RBPs including PCBP2 and SNRNP70 responsible for differential ASEs upregulated in BLCA with high-level neoplasm grade." (PMID 37810965, 2023). "PCBP2, as an RNA-binding protein, can bind and stabilize the expression of SCL7A11 mRNA, thereby inhibiting tumor ferroptosis and promoting tumor progression." (PMID 36147463, 2022).
tumor (continued). "Picrosirius red staining was performed to study the expression of collagen in the tumor tissue and to explore the mechanism by which the CCP/PCBP2 siRNA nanocomplex improved the antitumor efficacy of gemcitabine." (PMID 33500719, 2021). "As shown in the volcano plot, SU decreased GZMB expression and upregulated genes related to inflammatory activation (FOS, JUN, NFKBIA, DUSP2, JAK1, PIM1), tumor immunity (CD47, PCBP2, EIF5A, PDIA3, EGR1), and DNA damage (H2AFX, DDIT3, GADD45B)." (PMID 34824394, 2021). "Treatment with the CCP/PCBP2 siRNA nanocomplex reduces ECM production in vitro and in vivo, increasing antitumor drug delivery and penetration into the tumor microenvironment." (PMID 33500719, 2021). "SIRT6 inhibits PCBP2 expression by binding to PCBP2 promoter region and deacetylates H3K9, acting, therefore, as a tumor suppressor." (PMID 31591350, 2019). "Although certain details, such as the transcriptional activation of PCBP2 by EGFR and the validation of the PCBP2-miRNA complex in OSCC patients, still lack direct evidence, this study represents a significant contribution to the ongoing topic of EGFR-driven tumor angiogenesis." (PMID 39816681, 2025). "In conclusion, EGFR overexpression potentially stimulates the expression of PCBP2 through transcriptional regulation, and PCBP2 subsequently identifies GGGU motif-containing miRNAs to facilitate their secretion via sEVs, thereby promoting tumor angiogenesis." (PMID 39816681, 2025). "Furthermore, as the first identified small molecule inhibitors of PCBP1 and PCBP2, we evaluated the efficacy and safety of ACE-induced ferroptosis in tumor therapy." (PMID 40619432, 2025). "However, according to current reports, the role of PCBP1 and PCBP2 in tumor is completely opposite, PCBP1 can be considered as a tumor suppressor, and PCBP2 plays a carcinogenic role." (PMID 35907982, 2022). "Moreover, in some subsets including CD8 TEM, SU increased the level of tumor immunity-related genes, including CD47, PCBP2, EIF5A, and PDIA3." (PMID 34824394, 2021). "Also using our expression data, we identified several RNA processing factors that were differentially expressed between tumor subtypes and/or regulated by estrogen receptor, including YBX1, YBX2, MAGOH, MAGOHB, and PCBP2." (PMID 28263985, 2017). "Beyond its role in cGAS inhibition, PCBP2 may also interact with other immunosuppressive mechanisms, such as the TGF-β/Smad pathway or ECM remodeling, further contributing to an immune-resistant tumor microenvironment." (PMID 40051782, 2025). "Finally, we identified several RNA binding proteins such as PCBP2, SNRNP70, and HuR, which might contribute to splicing differences between different groups of neoplasm grade in BLCA." (PMID 37810965, 2023). "Finally, we identified several RBPs such as PCBP2, SNRNP70, HuR, and TIA1, which might contribute to splicing differences between different groups of neoplasm grade in BLCA." (PMID 37810965, 2023). "The results showed that ASEs up-regulated in BLCA with high-level neoplasm grade were enriched to several RBPs’ motifs, including “poly-T” motifs and polypyrimidine tract (Py-tract) sequence of HuR, CPEB4, TIA1, HNRNPC, PTBP1, RALY and ZC3H14, and motifs of PCBP2 and SNRNP70." (PMID 37810965, 2023). "Knocking out PCBP2 in CAL27 cells did not alter their proliferation and apoptosis in vitro, but notably inhibited the tumor growth in vivo." (PMID 39816681, 2025).
cancer (24 papers, 2012 to 2025). A tumor composed of atypical neoplastic, often pleomorphic cells that invade other tissues. "PCBP2, an RNA-binding protein, plays a crucial role in regulating cancer-associated biological processes." (PMID 39430249, 2024). "Taking the criteria of high relative abundance and strong association with cancer as the standard, Poly(rC)-binding protein 2 (PCBP2) was the target protein, and other protein information were shown at Supp." (PMID 37814239, 2023). "To further analyze the expression of PCBP2 across various cancers, we examined data from the TCGA-GTEx and TCGA databases." (PMID 40051782, 2025). "A few studies showed that PCBP2 played a vital role in several diseases, especially in the occurrence and development of cancer." (PMID 36147463, 2022). "Expression outliers of PCBP2 co-occurred with aberrant splicing of a large number of cancer-related genes, including CTNNB1 and CDK4." (PMID 32025019, 2020). "Our results thus further support the possible role of PCBP2 in regulating the splicing of cancer-related genes." (PMID 32025019, 2020). "The poly(C)-binding protein 2 (PCBP2), which is recognized for its direct interactions with single-stranded poly (C) motifs, has been identified as a prognostic marker and potential therapeutic target in a variety of cancer types." (PMID 40051782, 2025). "Many studies have shown that PCBP2 expression is elevated in various cancers." (PMID 39816681, 2025). "Results displayed that PCBP2 ranked first and was most correlated with cancer." (PMID 37814239, 2023). "PCBP2 can affect biological processes and cancer progression through RNA binding pathways." (PMID 36147463, 2022). "PCBP2 plays important roles in a series of cancers, and its functions are based on RNA binding." (PMID 31501420, 2019). "Studies had shown that when PCBP2 was knocked out, the expression of FHL3 in cancer cells was increased, thus inhibiting cell growth and promoting cell apoptosis." (PMID 37814239, 2023). "Our results indicate that poly(C)-binding protein 2 (PCBP2) influences the prognosis of PCa by suppressing the cGAS-STING pathway, which potentially upregulates inhibitory immune checkpoints such as PD-L1, and by promoting cancer cell mitosis." (PMID 40051782, 2025). "Related studies had shown that when PCBP2 was knocked out, the expression of pro-apoptotic factor Bax was increasing and anti-apoptotic factor Bcl-2 was decreasing, and caspase-3 and PARP were activated to mediate apoptosis of cancer cells." (PMID 37814239, 2023).
infection (17 papers, 2011 to 2026). The state of being infected such as from the introduction of a foreign agent such as serum, vaccine, antigenic substance or organism. "Expectedly, VSV stimulation caused cytoplasmic translocation of PCBP2 post 8-h infection." (PMID 26348439, 2015). "Therefore we conclude that the rabies virus G mRNA selectively associates with the cellular PCBP2 protein during infection." (PMID 22438951, 2012). "LD infection also decreased intact PCBP2 protein band with concomitant appearance of multiple faster migrating bands suggesting its multiple cleavage because of infection." (PMID 36309090, 2022). "Intact PCBP1 band became almost undetectable within 30 min of infection in J774 cells, whereas intact PCBP2 level was decreased steadily with increasing time of infection as detected in Western blots." (PMID 36309090, 2022). "We also detected decreasing trend of PCBP1 and PCBP2 protein levels with increase in multiplicity of infection (MOI = 1:1, 1:5, 1:10, and 1:20; 2 h) and simultaneous appearances of faster migratory band(s)." (PMID 36309090, 2022). "The expression profiles of the negative regulators PSMA7 and PCBP2 were similar at both the RNA and protein levels, and increased slowly during infection." (PMID 30642258, 2019). "The protein levels of PCBP2 were significantly upregulated by antagomir-HA-3p compared to treatment with control antagomir at 24 and 48 h post-infection." (PMID 29327729, 2018). "In our study, several proteins involved in inflammation and infection processes, such as Annexin A1, Complement component 1 Q subcomponent-binding protein (C1qBP), Poly(rC)-binding protein 2 (hnRNP E2) are indentified." (PMID 24454774, 2014). "In this study we demonstrate that the rabies virus G mRNA is differentially over-expressed during infection compared to other viral transcripts and that it selectively interacts with the cellular PCBP2 protein." (PMID 22438951, 2012). "During infection, the rabies virus glycoprotein mRNA also selectively interacts with the cellular poly(rC)-binding protein 2 (PCBP2), a factor known to influence mRNA stability." (PMID 22438951, 2012). "Co-localization of PCBP2 and SRp20ΔRRM suggests that these two proteins are in close proximity in the cytoplasm of the cell during infection." (PMID 21779168, 2011). "At 3 hours post-infection SRp20 re-localized to the cytoplasm of the infected cell and partially co-localized with PCBP2." (PMID 21779168, 2011). "We observed a dramatic re-localization of SRp20 from the nucleus to the cytoplasm of poliovirus-infected cells, where we also observed partial co-localization with PCBP2 during infection." (PMID 21779168, 2011). "If PCBP2 is sequestered away from functional viral translation complexes, this would hinder the progression of the infection and result in lower titers of virus produced." (PMID 21779168, 2011). "We were able to determine that SRp20ΔRRM partially co-localizes with PCBP2 at 3 hours post-infection in the cytoplasm of the infected cell." (PMID 21779168, 2011). "Taken together, these findings imply that Leishmania-induced GP63-mediated cleavage of PCBP1 and PCBP2 may help the parasite, particularly in the early stage of infection." (PMID 36309090, 2022). "PCBP2 sumoylation mediated by IRTKS took place in the nucleus on RNA virus infection, which causes its cytoplasmic translocation to interact with MAVS during the late stage of infection, leading to MAVS degradation." (PMID 26348439, 2015). "Although the interaction between PCBP2 and S-L I may aid in the stimulation of viral protein synthesis early during infection, it is the presence of 3CD and subsequent interactions with PCBP2 that allows the viral RNA replication process to proceed." (PMID 26150805, 2015). "We examined cells at 3 hours post-infection because sufficient amounts of SRp20 would be expected to be re-localized into the cytoplasm of the cell, where potential co-localization with PCBP2 could be visualized." (PMID 21779168, 2011).